ITCH (itchy E3 ubiquitin protein ligase)
Diseases named in the same sentence as ITCH in open-access papers (continued):
Sharing a sentence is not in itself a finding about the gene and the disease.
esophageal squamous cell carcinoma (33 papers, 2015 to 2023). Esophageal squamous cell carcinoma (ESCC) is a type of esophageal carcinoma (EC) that can affect any part of the esophagus, but is usually located in the upper or middle third. "Cir-ITCH has been implicated in esophageal squamous cell carcinoma (ESCC)." (PMID 27903978, 2017). "Recent studies have uncovered several dysregulated circRNAs, including hsa_circ_001059, hsa_circ_000167, hsa_circ_0067934, and cir-ITCH, in esophageal squamous cell carcinoma (ESCC), which is the seventh most common cause of cancer related death in American Men." (PMID 28969099, 2017). "For instance, cir-ITCH acts as a tumor suppressor in esophageal squamous cell carcinoma via sponging miR-7, miR-17, and miR-214." (PMID 32850833, 2020). "Not surprisingly, circ-ITCH has been reported to antagonize miR-7, miR-17 and miR-214, to upregulate ITCH and impede lung and esophageal squamous cell carcinoma growth by blocking the Wnt/β-catenin pathway." (PMID 29702599, 2018). "For instance, circular RNA that spans several exons of Ubiquitin (Ub) protein ligase 3 (E3) (cir-ITCH) can regulate the Wnt pathway by increasing the level of ITCH in esophageal squamous cell carcinoma." (PMID 30161026, 2018). "Three papers reported that cir-ITCH is downregulated in esophagus squamous cell carcinoma (ESCC), CRC, and lung cancer." (PMID 29911069, 2018). "Lately, the report showed that the expression of circRNA ITCH was usually low in esophageal squamous cell carcinoma compared with normal tissues." (PMID 27484176, 2016). "In addition, the circular isoform of the coding gene Itchy E3 Ubiquitin Protein Ligase (ITCH), cir-ITCH functions as a sponge for miR-7, miR-17, and miR-214 in esophageal squamous cell carcinoma (ESCC)." (PMID 30018188, 2018). "Similarly, a study in esophageal squamous cell carcinoma, showed that cir-ITCH, has a sponging effect on miRNAs, stimulating ITCH levels, promoting tumor development and progression." (PMID 29207676, 2017). "As sponge of oncogenic miR-7, miR-17, and miR-214, cir-ITCH increases the level of ITCH and thus indirectly inhibits the activation of Wnt/β-catenin pathway; these effects finally result in the suppression of esophageal squamous cell carcinoma and colorectal cancer." (PMID 27642589, 2016). "Elevated levels of circRNA_100367 were observed in radioresistant esophageal cancer cell lines, while the expression of cir-ITCH was downregulated in esophageal squamous cell carcinoma (ESCC) tissues." (PMID 35513849, 2022). "Further, in esophageal squamous cell carcinoma (ESCC), circ-ITCH perform a sponging action against miR-7, miR-17, and miR-214." (PMID 35087404, 2021). "In ESCC (oesophageal squamous cell carcinoma), cir-ITCH can increase ITCH expression by sponging miR-7, miR-14 and miR-214, and elevated ITCH levels inhibit ESCC tumourigenesis by suppressing the Wnt/β-Catenin pathway." (PMID 33060778, 2020). "(2015a) showed that circ‐ITCH is downregulated in esophageal squamous cell carcinoma (ESCC) and it is able to influence the expression level of its host gene, ITCH." (PMID 30719845, 2019). "It is validated that circ-ITCH resists miR-7, miR-17, and miR-214, while upregulating ITCH by blocking the Wnt/β-catenin pathway, thereby impeding the growth of NSCLC and esophageal squamous cell carcinoma (ESCC)." (PMID 35697671, 2022). "The expression of various circRNAs is dysregulated in esophageal squamous cell carcinoma (ESCC), for instance, circ- ITCH, hsa_circ_000167, hsa_circ_001059 and hsa_circ_0067934." (PMID 32467674, 2020). "And cir-ITCH as miR-7, miR-17 and miR-214 sponges may have a tumor suppressive role in esophageal squamous cell carcinoma (ESCC) while cir-ITCH as miR-7 and miR-214 sponges takes part in lung cancer." (PMID 28969093, 2017). "During the development of esophageal squamous cell carcinoma (ESCC), circITCH serves as a sponge for miR-7, miR-17 and miR-214, thereby increasing levels of the ITCH mRNA, inhibiting the Wnt/β-catenin pathway." (PMID 32309571, 2015).
esophageal squamous cell carcinoma (continued). "Also, Cir-ITCH has been reported sponging various miRNAs such as miR-20a and miR-7 in CRC and miR-7, miR-17, and miR- 214 in esophageal squamous cell carcinoma." (PMID 32467674, 2020). "Cir-ITCH was also shown to inhibit the development and progression of CRC and ESCC (esophageal squamous cell carcinoma)." (PMID 28279183, 2017).
breast cancer (25 papers, 2014 to 2026). A primary or metastatic malignant neoplasm involving the breast. "Our findings revealed novel cross-organ pathogenic communication between breast cancer and the heart through the exosomal miR-216a-5p-mediated ITCH/TXNIP/NLRP3 pathway, which drives cardiomyocyte pyroptosis." (PMID 40360476, 2025). "Here we demonstrate that FAM189A2, a downregulated gene in breast cancer, encodes a new type of ITCH activator." (PMID 34927784, 2022). "Future clinical studies correlating the ITCH mutational status with WBP2 protein expression would offer greater clarity on the prevalence of the ITCH/WBP2 signaling axis on breast cancer." (PMID 32393834, 2020). "It was shown that in order to mediate TGF-β-induced breast cancer invasion, ITCH must degrade Ras association domain family 1 isoform A (RASSF1A)." (PMID 30619734, 2018). "We found that ITCH knockdown resulted in reduced tumor volume and weight indicating that ITCH knockdown is associated with reduced breast cancer cell tumorigenesis." (PMID 25350971, 2014). "Furthermore, while overexpression of ITCH expression in breast cells is associated with increased incidence of mammary tumor formation and progression, its knockdown inhibited breast cancer cell tumorigenicity and metastasis." (PMID 25350971, 2014). "Furthermore, while overexpression of ITCH in breast cancer cells is associated with increased incidence of mammary tumor formation in vivo, its knockdown inhibited breast cancer cell tumorigenicity and reduced their metastatic potential, both, in vitro and in vivo." (PMID 25350971, 2014). "In breast cancer, inhibited expression of ITCH led to an increase in the activity of the Wnt/β-catenin signaling promoting the growth of breast cancer in vitro and in vivo." (PMID 40136647, 2025). "Collectively, these data suggests that O-GlcNAcylation of GATAD2B can regulate its ubiquitination and interaction with E3 ligase ITCH and thus contribute to O-GlcNAc-mediated regulation of cancer stem cell phenotypes and chemoresistance in breast cancer cells." (PMID 40136647, 2025). "Together, these data suggests that OGT and O-GlcNAc protects GATAD2B from proteasome-dependent degradation mediated by the E3 ligase ITCH and also identifies ITCH as a regulator of breast cancer stem cell functions." (PMID 40136647, 2025). "ITCH acts as a cancer-promoting factor in breast cancer, pancreatic cancer, hepatocellular carcinoma, and chronic lymphocytic leukemia." (PMID 33968776, 2021). "Collectively, the evidence further supports the notion of WBP2 as an oncogene that is downregulated by ITCH tumor suppressor-mediated proteasomal degradation in at least a subset of aggressive breast cancers." (PMID 32393834, 2020). "c-FLIP degradation via JNK/ITCH activation has been recently described to sensitize tamoxifen-resistant breast cancer to TRAIL-induced cell death." (PMID 31443721, 2019). "In a recent publication, ITCH was shown to sensitize ER+ breast cancer cells, who acquired resistance to endocrine treatment." (PMID 30619734, 2018). "E3 ubiquitin ligase ITCH plays a role in erythroid and lymphoid cell differentiation and immune response regulation, and ITCH was found to be important in the cross-talk between the Wnt and Hippo pathways in breast cancer development." (PMID 28957356, 2017). "The E3 ubiquitin ligase ITCH has been previously reported to inhibit the tumor suppressive Hippo signaling by suppressing LATS1/2 in breast cancer and chronic lymphocytic leukemia." (PMID 26621835, 2016). "In fact, a positive correlation between ITCH and tumor progression has been suggested in breast cancer, and chronic lymphocytic leukemia." (PMID 26621835, 2016). "Kaplan-Meier analysis revealed that high expression of ITCH was associated with shorter RFS (n=3455), shorter OS (n=1115), shorter DMFS (n=1609) and shorter PPS (n=351) in breast cancer patients." (PMID 25350971, 2014).
breast cancer (continued). "To further decipher the role of ITCH on breast cancer progression into a metastatic disease, we examined lungs of these mice by staining for p-Erk, a downstream effector of RAS." (PMID 25350971, 2014). "To support our in vitro findings that convincingly demonstrated that ITCH enhances the invasiveness of breast cancer cells, we decided to test ITCH depletion on seeding metastasis." (PMID 25350971, 2014). "Next, we tested the correlation between ITCH expression and it's prognostic value in the different breast cancer subtypes, basal, luminal A, luminal B and HER+." (PMID 25350971, 2014). "To this end we knocked down ITCH in the aggressive metastatic breast cancer cell line MDA-MB435 using small hairpin (ShRNA) constructs expressed in lentiviral vectors." (PMID 25350971, 2014). "To explore the prognostic value of ITCH expression in breast cancer, we evaluated mRNA expression of ITCH from publicly gene expression data set using the Kaplan-Meier Plotter resource." (PMID 25350971, 2014). "To show the human relevance of ITCH expression in breast cancer, we stained tissue microarrays (TMAs) for ITCH and YAP using immunohistochemistry." (PMID 25350971, 2014). "Kaplan-Meier analysis revealed that high expression of ITCH is associated with shorter RFS (n=1678) and shorter OS (n=504) in luminal A breast cancer patients." (PMID 25350971, 2014). "Our findings clearly indicate that ITCH positively regulates proliferation, survival and invasion of breast cancer cells." (PMID 25350971, 2014). "Altogether, these results clearly demonstrate that ITCH knockdown inhibits MDA-MB231 breast cancer cell growth, survival and invasion in vitro and metastasis in vivo further confirming that these effects are not cell specific." (PMID 25350971, 2014). "ITCH depletion in two metastatic breast cancer cells hampers their cell proliferation and survival, inhibits invasion ability and attenuated tumor growth and metastatic potential." (PMID 25350971, 2014). "Together, our results reveal that ITCH pro-tumorigenic functions in breast cancer are mediated, at least in part, through inactivation of the Hippo tumor suppressor pathway." (PMID 25350971, 2014). "To demonstrate the human relevance of our findings, we tested ITCH expression in human breast cancer tissue samples and found that ITCH expression is significantly upregulated in invasive and metastatic breast cancer cases." (PMID 25350971, 2014). "In fact, high expression of ITCH was observed in the majority (64%) of advanced stages of breast cancer cases." (PMID 25350971, 2014). "Similarly, circ-ITCH, though more extensively studied in other breast cancer subtypes, functions as a tumor suppressor by stabilizing ITCH-mediated ubiquitination of Dvl proteins, thereby inhibiting Wnt/β-catenin activation." (PMID 41516402, 2026). "The function of ITCH in regulating CSCs in breast cancer could be, in part, a result of ITCH regulation on GATAD2B stability." (PMID 40136647, 2025). "Here, we show for the first time that GATAD2B is critical in maintaining and promoting CSCs phenotypes while O-GlcNAcylation of GATAD2B enhances its stability and protects from ITCH-mediated proteasomal degradation and contributes to cancer stem cell functions in breast cancer cells." (PMID 40136647, 2025). "Circ-ITCH’s role in the aetiology of breast cancer is clearly apparent." (PMID 37370928, 2023). "This may be attributed to their effect on the level of circ-ITCH mRNA expression in breast cancer tissues as well as the level of β-cateinin in BC patients." (PMID 37370928, 2023). "Collectively, these results and the significant correlation of FAM189A2 downregulation with the poor long‐term prognosis of breast cancer patients illustrate that FAM189A2 is a new activator for ITCH that impacts the biology of cancer cells by regulating the CXCR4 desensitization process." (PMID 34927784, 2022).
breast cancer (continued). "Downregulation of circ-ITCH was observed in breast cancer (BC), and a new study showed that circ-ITCH could downregulate the Wnt/β-catenin signaling pathway by sponging miR-214 and miR-17." (PMID 34162394, 2021). "9F7-F11 could be useful to bypass resistance to chemotherapy in breast cancer by favoring c-FLIP degradation via JNK/ITCH activation." (PMID 31443721, 2019). "The DHX35 gene has previously been identified as a 5′ fusion partner to the ITCH gene in the SK-BR-3 breast cancer cell line, indicating that it may be a 5′ partner in multiple fusion genes." (PMID 26474385, 2015). "Our results obtained from the overexpression system prompted us to test whether ITCH knockdown inhibits the tumorigenic phenotype of breast cancer cells." (PMID 25350971, 2014). "Furthermore, high ITCH mRNA has a prognostic value as it correlates with worse survival of luminal A breast cancer patients." (PMID 25350971, 2014). "In the current study we investigated the pro-tumorigenic function of ITCH in breast cancer." (PMID 25350971, 2014). "Furthermore, ITCH knockdown inhibits breast cancer cell tumorigenicity and invasiveness, both in vitro and in vivo." (PMID 25350971, 2014). "In triple-negative breast cancer (TNBC), ITCH expression exceeds that found in luminal BC cells and normal mammary epithelial cells." (PMID 40535763, 2025). "Besides, a combination treatment by NEDD4-1 and WWP1 inducers for melanoma cancer, NEDD4-1 and ITCH inhibitors for prostate cancer, NEDD4-1 and SMURF1 for the HCC, as well as SMURF2 inducers and ITCH inhibitors for the breast cancer can be considered as the effective therapeutic approaches." (PMID 36918822, 2023). "Genetic inhibition of ITCH enhances the stability of GATAD2B, mammosphere formation and expression of CSCs factors in breast cancer cells." (PMID 40136647, 2025). "Together, we identify a key role of GATAD2B and ITCH in regulating CSCs in breast cancer and GATAD2B O-GlcNAcylation as a mechanism regulating breast cancer stem-like populations and promoting chemoresistance." (PMID 40136647, 2025). "Together, these data show a crucial role of ITCH in mediating GATAD2B levels and regulating CSCs in breast cancer." (PMID 40136647, 2025). "Here, we showed that genetic inhibition of ITCH increased expression of GATAD2B, SOX2 and MYC, as well as mammosphere formation and CSCs population detected by ALDEFLOUR in multiple breast cancer cell lines." (PMID 40136647, 2025). "ITCH knockdown increased the level of GATAD2B, but also elevated the mammosphere formation of breast cancer cells and increased cancer stem cell factors SOX2 and c-Myc." (PMID 40136647, 2025). "Another PROTAC tractable target is Rac Family Small GTPase 1 (RAC1), inducing chemoresistance of breast cancer, interacts with co-opted E3 ligases MDM2 and XIAP, and potentially novel E3 ligases, ITCH and SMURF2." (PMID 37845222, 2023). "The authors showed that wnt signaling blocks ITCH mediated degradation of YAP/TAZ transcriptional coactivator WBP2, and thus promotes breast cancer cell proliferation." (PMID 30619734, 2018). "In particular, we show that ITCH enhances EMT, mammary tumor formation and metastasis through boosting YAP oncogenic function." (PMID 25350971, 2014). "To further confirm that ITCH is a pro-invasive factor in breast cancer, we tested the effect of ITCH knockdown on the invasive potential of MDA-MB435 breast cancer cells using a Boyden chamber Matrigel invasion assay." (PMID 25350971, 2014). "In addition, The LPxY motif‐containing tumor suppressor WW domain‐containing oxidoreductase (WWOX) is also an ITCH substrate; depletion of WWOX induces anchorage‐independent proliferation of MCF‐7 cells, and knockout mice of this gene develop mammary tumors." (PMID 34927784, 2022). "To elucidate whether ITCH is expressed at equal frequency in the different breast cancer subtypes, we analyzed our TMA for the distribution of ITCH in ER+, HER2+, and triple-negative invasive breast cancers." (PMID 25350971, 2014).
breast cancer (continued). "Label free proteomic results showed an increase in the level of ITCH, an E3-ligase, co-immunoprecipitated in OMSi treatment when compared to DMSO or TMG treatment, suggesting that ITCH may ubiquitinate GATAD2B in breast cancer cells." (PMID 40136647, 2025). "Detailed characterization of ITCH-mediated phenotypes both in vitro, using Gelfoam cultures, and in vivo, using high quality GFP tumor and cellular imaging, shall be required to further decipher ITCH protumorigenic functions in breast cancer progression and metastasis." (PMID 25350971, 2014).
colorectal cancer (17 papers, 2016 to 2025). A primary or metastatic malignant neoplasm that affects the colon or rectum. "In colorectal carcinoma, the loss of ITCH expression is associated with carcinogenesis, and ITCH might be involved in the Notch-1 pathway during colorectal carcinoma progression." (PMID 37760946, 2023). "The circ-ITCH regulates the Wnt/catenin signalling pathway in colorectal cancer cells, and its expression was approximately 75.6% higher in cancer-adjacent tissue than in cancer-matched tissue." (PMID 37370928, 2023). "This is in line with an identified role for ITCH as an inhibitor of the Wnt signaling pathway which holds a prominent role in colorectal cancer development and progression." (PMID 34771517, 2021). "For example, cir-ITCH, which functions as an miRNA sponge to increase ITCH expression levels, is found downregulated in colorectal cancer tissues compared to control." (PMID 34771517, 2021).